SLC23A1 (solute carrier family 23 member 1)
Description:
Sodium:ascorbate cotransporter. Mediates electrogenic uptake of vitamin C, with a stoichiometry of 2 Na(+) for each ascorbate. Has retained some ancestral activity toward nucleobases such as urate, an oxidized purine. Low-affinity high-capacity sodium:urate cotransporter, may regulate serum urate levels by serving as a renal urate re-absorber. [Isoform 2]: Inactive transporter.
Synonyms: SVCT1; YSPL3; SLC23A2
Tractability: Small molecule: a structure with a bound ligand is known. Antibody: UniProt places it where antibodies can reach, with high confidence; its Gene Ontology location is reachable by antibodies, with high confidence; UniProt predicts a signal peptide or a membrane-spanning region. PROTAC: its protein half-life has been measured.
Target class: Electrochemical transporter; SLC23 family of ascorbic acid transporters; Transporter; SLC superfamily of solute carriers
Gene: Protein-coding gene on chromosome 5 (139,367,196 to 139,385,495, reverse strand). Ensembl gene ENSG00000170482.
Subcellular location: Cell membrane
Pathways (Reactome):
Metabolism: Vitamin C (ascorbate) metabolism
Gene Ontology:
Molecular function: dehydroascorbic acid transmembrane transporter activity; L-ascorbate:sodium symporter activity; L-ascorbic acid transmembrane transporter activity; protein binding; sodium ion transmembrane transporter activity; urate transmembrane transporter activity; nucleobase transmembrane transporter activity; transmembrane transporter activity
Biological process: dehydroascorbic acid transport; L-ascorbic acid transmembrane transport; response to toxic substance; sodium ion transport; brain development; L-ascorbic acid metabolic process; nucleobase transport; lung development; sodium ion transmembrane transport; transmembrane transport; urate transport
Cellular component: apical plasma membrane; extracellular exosome; intracellular organelle; plasma membrane; cytoplasm; basal plasma membrane; membrane
Genetic constraint (gnomAD): Loss-of-function variants: 26 observed, 52.55 expected, observed/expected ratio (o/e) 0.49, 90% interval 0.36 to 0.69. The upper end of that interval is the gene's LOEUF score, 0.69, which puts it in group 2 of 6, group 1 being the genes least tolerant of losing a copy. Missense variants: 597 observed, 715.65 expected, observed/expected ratio (o/e) 0.83, 90% interval 0.78 to 0.89. Synonymous variants: 251 observed, 282.47 expected, observed/expected ratio (o/e) 0.89, 90% interval 0.8 to 0.99.
Homologues: Orthologues: chimpanzee SLC23A1 (99% identical), macaque SLC23A1 (97% identical), rat Slc23a1 (91% identical), mouse Slc23a1 (91% identical), pig SLC23A1 (91% identical), guinea pig SLC23A1 (91% identical), rabbit SLC23A1 (86% identical), zebrafish slc23a1 (73% identical), tropical clawed frog slc23a1 (71% identical), Drosophila melanogaster CG6293 (41% identical). Paralogues in human: SLC23A2 (63% identical), SLC23A3 (28% identical).
Diseases named in the same sentence as SLC23A1 in open-access papers:
SLC23A1 is named in the same sentence as 31 diseases in open-access papers, as found by Europe PMC text mining. Sharing a sentence is not in itself a finding about the gene and the disease. The quoted sentences say what the papers report.
gastric cancer (2 papers, 2020). A primary or metastatic malignant neoplasm involving the stomach. "Since SVCT1 is responsible for vitamin C absorption and reabsorption, it is possible to find the SLC23A1 SNP in gastric cancers." (PMID 33352824, 2020). "Another study showed SLC23A2 polymorphism was associated with gastric cancer but SLC23A1 polymorphism was not." (PMID 32899442, 2020).
hyperuricemia (2 papers, 2021 to 2023). An abnormally high level of uric acid. "The SLC23A1 gene variant linked to high plasma vitamin C did not result in different plasma urate levels or a lower risk of developing hyperuricemia." (PMID 33671646, 2021). "However, the SLC23A1 genetic variant causing long-term high plasma VC was not decrease SUA levels or hyperuricemia risk in Mendelian randomization study including 106,147 individuals." (PMID 37831704, 2023).
periodontitis (2 papers, 2020 to 2022). An acute or chronic inflammatory process that affects the tissues that surround and support the teeth. "An investigation demonstrated a positive association between a loss of functional variant of the SLC23A1 vitamin C transporter and periodontitis, suggesting that genetic factors might affect periodontitis indirectly through a lack of functional provision of important substrates." (PMID 35565905, 2022).
breast carcinoma (1 paper, 2024). "Moreover, the ascorbate level in the plasma of breast cancer patients was decreased with the accompanying increase of sodium-dependent vitamin C transporters (SLC23A1 and SLC23A2)." (PMID 38499584, 2024). "Moreover, mRNA expression of SLC23A1 and SLC23A2 was elevated in leukocytes from breast cancer patients." (PMID 38499584, 2024). "Interestingly, we found higher mRNA expression of vitamin C transporters (SLC23A1 and SLC23A2) in breast cancer patients in comparison to control samples." (PMID 38499584, 2024).
colorectal cancer (1 paper, 2022). A primary or metastatic malignant neoplasm that affects the colon or rectum. "The SLC23A1 variant had a strong association with small intestine cancer and colorectal cancer in both FinnGen and UK Biobank." (PMID 35986965, 2022).
Crohn disease (1 paper, 2025). A gastrointestinal disorder characterized by chronic inflammation involving all layers of the intestinal wall, noncaseating granulomas affecting the intestinal wall and regional lymph nodes, and transmural fibrosis. "Polymorphisms in SLC23A1 have been shown to predict plasma vitamin C levels and tissue distribution, and are associated with an increased risk of Crohn’s disease." (PMID 40722932, 2025).
follicular lymphoma (1 paper, 2020). Follicular lymphoma is a form of non-Hodgkin lymphoma characterized by a proliferation of B cells whose nodular structure of follicular architecture is preserved. "A large population-based case–control study revealed that SLC23A1 rs6596472 and SLC23A1 rs11950646 may increase the risk of follicular lymphoma by up to 80%." (PMID 33352824, 2020).
intracerebral hemorrhage (1 paper, 2019). A cerebrovascular disorder characterized by bleeding into one or both cerebral hemispheres including the basal ganglia and the cerebral cortex. "A deficiency of SLC23A1 in mice causes respiratory failure and intracerebral hemorrhage in newborn mice, implying that SLC23A1 is essential for lung alveolar expansion and blood vessel development in the brain." (PMID 30239845, 2019).
lymphoma (1 paper, 2008). A malignant (clonal) proliferation of B- lymphocytes or T- lymphocytes which involves the lymph nodes, bone marrow and/or extranodal sites. "Other associations were observed between risk of lymphoma subtypes and SLC23A1, SLC23A2, and MMP9 SNPs." (PMID 18636124, 2008). "Thus, the influence of SLC23A1 and SLC23A2 genetic variation on NHL risk suggests that both vitamin C uptake and storage may be involved in the pathogenesis of lymphoma." (PMID 18636124, 2008).
type 1 diabetes (1 paper, 2020). "However, a common variant in the SLC2A2 gene (rs5400) was associated with an increased risk of type 1 diabetes, while a less frequent variant in SLC23A1 (rs33972313) showed an association of borderline statistical significance." (PMID 31728565, 2020). "Furthermore, SNP rs33972313 in SLC23A1 was associated with lower plasma ascorbic acid concentrations, in line with previous studies, and appeared to increase type 1 diabetes risk, although the finding was of borderline significance (p = 0.06)." (PMID 31728565, 2020). "Furthermore, SLC23A1 rs33972313 did not modify the association between plasma ascorbic acid and the risk of islet autoimmunity or type 1 diabetes, IAA first (interaction p = 0.43) or GADA first (interaction p = 0.10)." (PMID 31728565, 2020).
type 2 diabetes (1 paper, 2023). "In the case of type 2 diabetes, of the 11 genomic regions association with ascorbate plasma concentration in 80,983 cases and 842,909 noncases, the strongest signal was found with SLC23A1, the vitamin C transporter SVCT1, with a significant signal also with SLC23A3, the orphan transporter SVCT3." (PMID 36766828, 2023).
cancer (8 papers, 2017 to 2024). A tumor composed of atypical neoplastic, often pleomorphic cells that invade other tissues. "Different single nucleotide polymorphisms (SNPs) have been shown to weaken ascorbate transport and to reduce plasma levels with a trend toward a higher cancer risk for SLC23A1 variants." (PMID 37107291, 2023). "Even in the literature reports it is still not clear how the phosphate transportation or concentration level and absorption via SLC23A1 of ascorbate influences the cancer cells." (PMID 33287006, 2020).
infection (2 papers, 2023 to 2024). The state of being infected such as from the introduction of a foreign agent such as serum, vaccine, antigenic substance or organism. "In this study, the SLC23A1 gene is the only gene whose expression is up-regulated, which indicates that infection leads to an antioxidant reaction in cells, which induces the up-regulation of SLC23A1 expression so as to transport a large amount of L-ascorbic acid into cells to remove ROS." (PMID 39519375, 2024).
SLC23A1 also shares sentences with these, for which no sentence is quoted: tumor (3 papers); colon carcinoma (2); COVID-19 (2); age (1); ascorbic acid deficiency (1); bladder cancer (1); colitis (1); colon adenocarcinoma (1); diabetes (1); hepatoma (1); Hypernatremia (1); ischaemic heart disease (1); non-Hodgkin lymphoma (1); peripheral artery disease (1); pulmonary fibrosis (1); respiratory failure (1); Sepsis (1); small intestine cancer (1).